LACC1 (laccase domain containing 1)
Diseases named in the same sentence as LACC1 in open-access papers:
LACC1 is named in the same sentence as 40 diseases in open-access papers, as found by Europe PMC text mining. Sharing a sentence is not in itself a finding about the gene and the disease. The quoted sentences say what the papers report.
leprosy (19 papers, 2013 to 2025). Leprosy is a chronic infectious disease affecting primarily the skin and peripheral nervous system. "An association study in southwest China with the rs3764147 SNP, where genetic and expressional evidence points to LACC1 as a leprosy susceptibility gene." (PMID 41430577, 2025). "For example, SNVs in the C13orf31 (LACC1) gene that encodes p.C284R and p.I254V in FAMIN protein, are highly correlated with increased risk for systemic juvenile idiopathic arthritis, leprosy and Crohn's disease." (PMID 38742234, 2024). "We have previously published a replication analysis at rs3764147 (the leprosy-associated SNP at LACC1) in the Mali samples." (PMID 36121873, 2022). "We were able to replicate leprosy associations at 2 loci; a missense SNP in LACC1, rs3764147 (p = 0.004, OR = 1.36 95% CI 1.10 − 1.67), and a missense SNP in SLC29A3, rs780668 (p = 0.034, OR = 1.28 95% CI 1.02 − 1.60)." (PMID 36121873, 2022). "We also validated two previously identified risk factors for leprosy, a missense variant in the LACC1 gene, and an intergenic variant located close to the IL12B gene." (PMID 32421744, 2020). "The LACC1 leprosy susceptibility SNP rs3764147 is a missense variant (p.Ile254Val) first identified by a leprosy GWAS in the Han Chinese population and then replicated in Indian, African, Vietnamese, Yi, Wenshan and Yuxi Chinese populations." (PMID 32421744, 2020). "They found that a rare missense variant in HIF1A [MIM: 603348] and a common missense variant in LACC1 [MIM: 613409] contribute to leprosy susceptibility in Han Chinese." (PMID 33362202, 2020). "The first link between LACC1 and disease was identified through an association with leprosy and Crohn's disease (CD) by genome wide association studies (GWAS)." (PMID 30766537, 2019). "Recently, the LACC1 contribution to leprosy risk has been reinforced: a GWAS-based analysis focusing on functional variants detected association between leprosy and a LACC1 missense variant (rs3764147, c.760A > G, p.Ile254Val)." (PMID 30079069, 2018). "Genetic variation in the Laccase (multicopper oxidoreductase) domain-containing 1 (LACC1) gene has been shown to affect the risk of Crohn’s disease, leprosy and, more recently, ulcerative colitis and juvenile idiopathic arthritis." (PMID 27959965, 2016). "Of note, LACC1 SNPs represent strong genetic risk factors not only for CD but also for leprosy, and we have recently reported the occurrence of LACC1 common risk variants in UC and juvenile idiopathic arthritis (JIA) patients." (PMID 27959965, 2016). "GWAS have identified LACC1 as a core susceptibility gene for leprosy across various populations." (PMID 41376621, 2025). "We tested the six typical autoantibodies combined with LACC1, which encodes a protein associated with autoimmune disease such as Crohn’s disease and is also the susceptible gene conferring leprosy risk, in cured leprosy patients through ELISA to assess the cured patient’s immune status." (PMID 36604576, 2023). "Furthermore, we replicate previously identified leprosy susceptibility loci at LACC1, SLC29A3, and with HLA Class I and II alleles." (PMID 36121873, 2022). "We also validated two previously identified risk factors for leprosy: the missense variant rs3764147 in the LACC1 gene (OR = 1.52 [1.41–1.63], combined p-value = 5.06x10-14), and the intergenic variant rs6871626 located close to the IL12B gene (OR = 0.73 [0.61–0.84], combined p-value = 6.44x10-8)." (PMID 32421744, 2020). "Interestingly leprosy and Crohn's disease are both granulomatous disorders, and share the same LACC1 risk allele, the specific missense p.Ile254Val variant (rs3764147; MAF = 0.27)." (PMID 30766537, 2019). "Because the same LACC1 mutations, p.Ile254Val and p.Cys284Arg, have been associated with multiple phenotypes including, leprosy, BD, SoJIA and early-onset CD, it is likely that environmental factors, such as microbiota, play an important role in disease expressivity and manifestations." (PMID 30766537, 2019).
leprosy (continued). "Finally, LRRK2 is a negative regulator of inflammasome activation and an inducer of ROS production, two known mechanisms of immune defense against bacterial infections also modified by variants of LACC1, a gene consistently associated with leprosy." (PMID 30079069, 2018). "LACC1 genetic variants are associated with Crohn's disease, leprosy and arthritis." (PMID 28593945, 2017). "In doing so we replicate known leprosy susceptibility loci at MHC class I and II, LACC1 and SLC29A3." (PMID 36121873, 2022). "Notably, a strong positive relationship exists between LACC1 and autoantibodies in individuals who have recovered from leprosy." (PMID 41376621, 2025). "Furthermore, clinical observations reveal that autoantibodies persistently detectable in the bodies of cured leprosy patients exhibit a positive correlation with LACC1 expression." (PMID 41376621, 2025). "In our study, we selected ACA, ANA, ENA, ASO, dsDNA, and RF that had been reported in leprosy patients as typical autoantibodies, and tested the six typical autoantibodies combined with LACC1 in cured leprosy patients through ELISA to assess the cured patient's immune status." (PMID 36604576, 2023). "In addition to the HLA locus, we were able to consistently replicate the LACC1 and IL12B loci previously associated with leprosy in the Chinese population both in the discovery GWAS and the replication sample." (PMID 32421744, 2020). "Here, we investigated whether SNPs located in eleven genes: CCDC122/LACC1, IFNG, IL6, IL10, IL23R, LRRK2, NOD2, PACRG/PRKN, TLR1, TNF and TYK2 are associated to leprosy susceptibility in a population in the North of Brazil." (PMID 32433683, 2020). "Thus, the leprosy susceptibility loci, including NOD2, RIPK2, TNFSF15, LACC1, LRRK2, IL12B, and HLA‐DR in phagocytes and IL23R, TYK2, and CSK in T cells, may interfere with the synergistic antimicrobial response between phagocytes and T cells." (PMID 38020709, 2023). "Subsequently, associations between leprosy and the HLA-DR-DQ region, LACC1, CCDC122, and the I602S functional SNP in the Toll-like receptor 1 (TLR1) gene were replicated in an Indian population and between the HLA-DR-DQ, RIPK2, CCDC122, LACC1, and NOD2 in Vietnam." (PMID 23936864, 2013). "Indeed, while several genes with known overlap of IBD and leprosy were detected (i.e. RIPK2, LACC1 and IL23R), there was no genome-wide statistical enrichment for IBD risk alleles in T1R-free leprosy (p = 0.09)." (PMID 28222097, 2017).
Crohn disease (10 papers, 2016 to 2025). A gastrointestinal disorder characterized by chronic inflammation involving all layers of the intestinal wall, noncaseating granulomas affecting the intestinal wall and regional lymph nodes, and transmural fibrosis. "Relative to LACC1 Ile254, cells transfected with Crohn's disease-risk LACC1 Val254 or LACC1 with mutations of the nearby histidines have reduced PRR-induced outcomes." (PMID 28593945, 2017). "Here the authors show that LACC1 is needed for optimal innate receptor-induced signalling, mitochondrial ROS production and microbial clearance, effects that are reduced by a Crohn's disease-risk variant in LACC1." (PMID 28593945, 2017). "Loss of function mutations in LACC1 associate with several inflammatory diseases, such as juvenile idiopathic arthritis and Crohn’s disease, offering the interesting possibility that MRTFs may antagonize inflammation in part via upregulation of LACC1." (PMID 34671275, 2021).
Arthritis (9 papers, 2016 to 2024). Inflammation of a joint. "LACC1-deficient mouse models show an increased incidence of arthritis, psoriasis, T-cell metastatic colitis (Rag2−/− background), and intestinal bacterial infection (Citrobacter rodentium and Salmonella enterica serovar Typhimurium)." (PMID 37848840, 2023). "The study on a Moroccan family with severe arthritis that presented recessive inheritance showed that the frame shift mutation of LACC1/FAMIN, p.Cys43Tyrfs*6, was most likely the cause of polyarthritis RF-negative JIA." (PMID 33076506, 2020). "Our findings illuminate a previously unidentified pathway in inflammatory macrophages, explain why its deficiency may contribute to human inflammatory diseases, and suggest that L-Orn could serve as a nutraceutical to ameliorate LACC1-associated immunological dysfunctions such as arthritis or IBD." (PMID 35978195, 2022). "The LACC1 protein is highly expressed in inflammatory macrophages and plays an important regulatory role in many inflammatory diseases, such as arthritis and microbial infections." (PMID 37848840, 2023). "Among the regulation factors, laccase domain-containing protein 1 (LACC1) regulates TNF and IL-17 in mouse models of arthritis and inflammation." (PMID 32350307, 2020). "Laccase domain-containing 1 (LACC1) protein is an enzyme highly expressed in inflammatory macrophages and serves a central regulatory role in multiple inflammatory diseases, such as in inflammatory bowel diseases (IBDs), arthritis, and clearance of microbial infection." (PMID 35978195, 2022).
juvenile idiopathic arthritis (8 papers, 2016 to 2025). Juvenile idiopathic arthritis (JIA) is the term used to describe a group of inflammatory articular disorders of unknown cause that begin before the age of 16 and last over 6 weeks. "Kallinich T, Thorwarth A, von Stuckrad SL, Rösen-Wolff A, Luksch H, Hundsdoerfer P, Minden K, Krawitz P. Juvenile arthritis caused by a novel FAMIN (LACC1) mutation in two children with systemic and extended oligoarticular course." (PMID 37848930, 2023). "High consanguineous marriages in Arab countries provides an opportunity to find novel risk loci like LACC1 and LRBA that are associated with the monogenic juvenile idiopathic arthritis (JIA) and inflammatory bowel disease with combined immunodeficiency, respectively, in the Arab population." (PMID 34054914, 2021). "LACC1 mitigates inflammatory damage in juvenile idiopathic arthritis (JIA)." (PMID 41376621, 2025).
inflammatory bowel disease (6 papers, 2020 to 2025). A spectrum of small and large bowel inflammatory diseases of unknown etiology. "In the inflammatory bowel disease model, LACC1 KO mice developed more severe T-cell metastatic colitis, characterized by low levels of Th1/Th17 cytokines." (PMID 41376621, 2025). "The aim of this study was to explore the mechanism whereby LACC1 regulates the intestinal flora in a mouse model of inflammatory bowel disease (IBD)." (PMID 37848840, 2023). "The pathogenic LACC1 mutation I254V (c.760A > G, p.Ile254Val) causes a serious impairment of FAMIN and is considered associated with the development of non-systemic JIA, inflammatory bowel diseases, and Behçet disease." (PMID 36768167, 2023).
Still disease (4 papers, 2019 to 2025). "Recently, familial cases of systemic-onset JIA have been attributed to mutations in LACC1/FAMIN." (PMID 30872671, 2019). "Additional targeted sequencing studies performed in patients with systemic-onset JIA (n:23) and RF-negative polyarticular JIA (n: 44) revealed no pathogenic LACC1/FAMIN mutations." (PMID 30872671, 2019).
autoimmune disease (3 papers, 2016 to 2025). A disorder resulting from loss of function or tissue destruction of an organ or multiple organs, arising from humoral or cellular immune responses of the individual to their own tissue constituents. "The LACC1 gene has been identified through genome-wide association studies (GWAS) as a prevalent risk factor for several autoimmune diseases, including JIA, rheumatoid arthritis (RA), Behcet’s disease (BD), and psoriasis." (PMID 41376621, 2025). "As LACC1 is a master regulator in autoimmune diseases, we investigated whether the autoantibody levels were related to LACC1 protein levels." (PMID 36604576, 2023).
Autoimmunity (3 papers, 2022 to 2025). The occurrence of an immune reaction against the organism's own cells or tissues. "Conversely, in the arthritis model involving LACC1 KO mice, collagen II induced Th17 cell differentiation and a significant rise in IL-17, which resulted in impaired immune tolerance and facilitated the onset of autoimmunity." (PMID 41376621, 2025).
Behcet disease (3 papers, 2019 to 2025). A chronic, relapsing, multisystemic vasculitis characterized by mucocutaneous lesions, as well as articular, vascular, ocular and central nervous system manifestations. "For example, in Behcet’s disease and psoriasis, the functional role and mechanism of action of LACC1 require further elucidation." (PMID 41376621, 2025). "Later studies have demonstrated an association between a SNP (rs2121033; MAF = 0.27) downstream of LACC1 with Behcet's Disease." (PMID 30766537, 2019).
colitis (3 papers, 2020 to 2023). Inflammation of the colon. "Our results showed that, compared with WT mice, Lacc1−/− mice had a significantly higher DAI score after drinking 3% DSS (P < 0.05), reflecting the gradual aggravation of colitis." (PMID 37848840, 2023).
Cognitive impairment (1 paper, 2025). Abnormal cognition is characterized by deficits in thinking, reasoning, or remembering. "In models of anesthesia-induced cognitive impairment, the expression of LACC1 in mouse brain tissue is elevated." (PMID 41376621, 2025). "LACC1-related cognitive dysfunction primarily encompasses anesthesia-induced cognitive impairment and post-stroke cognitive impairment." (PMID 41376621, 2025). "Similarly, in cases of stroke-related cognitive impairment, LACC1 expression is also upregulated in cerebral ischemic tissues." (PMID 41376621, 2025). "This increase activates the LACC1/mROS signaling pathway, which induces the aggregation of NOD2 and the formation of NOD2-RIP2 complexes, ultimately leading to mitochondrial dysfunction in neurons and exacerbating cognitive deficits." (PMID 41376621, 2025).
enteritis (1 paper, 2023). Inflammation of the small intestine. "We found that Lacc1−/− mice showed congenital spontaneous enteritis, similar to the clinical symptoms of patients with IBD." (PMID 37848840, 2023).
enthesitis-related arthritis (1 paper, 2020). "Recently, studies found that recessive hereditary LACC1/FAMIN mutations were correlated with different subtypes of monogenic JIA, including sJIA, oligoarthritis, polyarthritis RF-negative, and enthesitis-related arthritis." (PMID 33076506, 2020).
lepromatous leprosy (1 paper, 2021). A chronic communicable infection which is a principal or polar form of leprosy. "Furthermore, we observed a prominent upregulation toward higher MOI (100:1) when genes associated with cholesterol and fatty acid metabolism (DHCR7, MVK, and MSMO, and LACC1/FAMIN were analyzed, which are pathways involved in lepromatous leprosy immunopathogenesis." (PMID 33936067, 2021).
Obesity (1 paper, 2025). Accumulation of substantial excess body fat. "In summary, BBOX1, SSTR1, MMP7, and LACC1 are identified as diagnostic markers of obesity and NAFLD." (PMID 39619480, 2025). "BBOX1, SSTR1, MMP7, and LACC1 emerged as common predictors for obesity and NAFLD through animal experimentation and predictive model analysis." (PMID 39619480, 2025). "Obesity and NAFLD share a molecular mechanism with BBOX1, SSTR1, MMP7, and LACC1, which play crucial roles in disease development and can serve as common predictors." (PMID 39619480, 2025).
psoriasis (1 paper, 2025). An autoimmune condition characterized by red, well-delineated plaques with silvery scales that are usually on the extensor surfaces and scalp. "Mutations in the LACC1 gene are linked to an increased susceptibility to psoriasis." (PMID 41376621, 2025). "In disease models, the absence of LACC1 exacerbates psoriasis-like symptoms, suggesting that this gene plays a protective role in disease regulation and offering a novel avenue for therapeutic research." (PMID 41376621, 2025).
Stroke (1 paper, 2025). Sudden impairment of blood flow to a part of the brain due to occlusion or rupture of an artery to the brain. "Research indicates that LACC1 expression is elevated in pathological states like surgery under anesthesia and stroke." (PMID 41376621, 2025).
infectious disease (3 papers, 2016 to 2025). A disorder directly resulting from the presence and activity of a microbial, viral, or parasitic agent in humans. "Furthermore, the article provides a comprehensive summary of the pathogenic mechanisms and recent advancements in research concerning LACC1 in immune diseases, metabolic disorders, infectious diseases, and neurological conditions." (PMID 41376621, 2025).
immune disorders (1 paper, 2025). "Furthermore, dysfunctions in LACC1 functionality have been linked to various immune disorders." (PMID 41376621, 2025).
infection (1 paper, 2025). The state of being infected such as from the introduction of a foreign agent such as serum, vaccine, antigenic substance or organism. "LACC1 serves as a pivotal regulatory factor in immune metabolism, crucial for preserving immune balance, orchestrating infection defense through the integration of metabolic pathways and immune reactions." (PMID 41376621, 2025).
LACC1 also shares sentences with these, for which no sentence is quoted: polyarticular JIA (2 papers); Sepsis (2); ulcerative colitis (2); arthropathy (1); autoimmune myocarditis (1); bacterial infection (1); chronic granulomatous disease (1); degenerative diseases (1); enthesitis (1); hepatocellular carcinoma (1); juvenile dermatomyositis (1); lipodystrophy (1); macrophage activation syndrome (1); metabolic disease (1); non-alcoholic fatty liver disease (1); polyarthritis (1); rheumatoid arthritis (1); tumor (1); uveitis (1); viral infection (1).